RASSF1 (Ras association domain family member 1)
Diseases named in the same sentence as RASSF1 in open-access papers (continued):
Sharing a sentence is not in itself a finding about the gene and the disease.
tumor (continued). "Several conventional NPC tumor suppressor genes, such as RASSF1 and CDKN2A (p16), were methylated at promoter regions in NPC patients from our Methyl-Cap sequencing data, but their expression levels were not significantly down-regulated in NPC by cDNA microarray analysis." (PMID 28716111, 2017). "RASSF1 was differentially methylated in Classic tumor tissue compared to Hurthle (p<0.001)." (PMID 27158284, 2015). "In our study RASSF1 hypermethylation varied between tumor subtypes, as observed in another study." (PMID 26284587, 2015). "RASSF1 is a tumor suppressor that is often silenced in NSCLC." (PMID 24489653, 2014). "Thus, the RASSF1 gene appears to play an important dual role in cancer, functioning alternatively as a tumor suppressor and as an oncogene." (PMID 25007054, 2014). "Thus, the inverse correlation between ANRASSF1 and RASSF1 expression in the public array datasets was confirmed in the one non-tumor and two tumor cell lines obtained from two different tissues." (PMID 23990798, 2013). "Taken together, our results reveal a novel mechanism for epigenetic regulation at the RASSF1 locus that involves the antisense unspliced lncRNA ANRASSF1, suggesting an inverse correlation between ANRASSF1 and RASSF1A expression in both tumor and non-tumor cell lines." (PMID 23990798, 2013). "It is well established that RASSF1–6 have tumor suppressor activity, and recent evidence suggests that other members of the family may also function as tumor suppressors." (PMID 22693671, 2012). "The calpain-mediated cleavage of NORE1A and RASSF1 tumor suppressors might be a mechanism by which some human tumors escape growth and tumor suppression." (PMID 19098985, 2008). "In addition, Ras association domain families 1 and 2 (RASSF1 and RASSF2), the negative regulators of K-ras, are often inactivated by methylation of the promoter region in those tumours." (PMID 17923875, 2007). "Moreover, RASSF1 gene methylation status has been shown to correlate with tumor behavior and could serve as a novel biomarker for predicting patient outcomes." (PMID 40142302, 2025). "Our analyses showed that the transcriptome associated with RASSF1, a tumor suppressor involved in cell cycle regulation and not previously linked to UPR, is highly correlated with the transcriptome of several UPR‐related genes, such as BiP/GRP78, DNAJB9, GRP94, ATF4, DNAJC3, and CHOP/DDIT3." (PMID 36723232, 2023). "However, they note that some studies had RASSF1 hypermethylation in non-tumour control samples." (PMID 34885067, 2021). "Furthermore, to confirm the tumor-origin of the PDCOs we have analyzed the expression of PC-associated epigenetic biomarkers including promoter methylation of the GSTP1, RASSF1 and APC and RARb genes by employing a novel microfluidic rare-event screening protocol." (PMID 34581895, 2021). "In addition to the discrimination between tumor and tumor-free samples, RASSF1 might be a suitable marker to differentiate high-grade NET from NSCLC." (PMID 29851970, 2018). "Other pathways, such as Ras (RAF1, RALBP1, RASSF1), TGF-β (CREB3L2/3, CREB5, TCL1A), Rap1, Hippo, and axonal guidance, further facilitate tumour migration and spread." (PMID 41007296, 2025). "Promoter methylation analysis was conducted for the following tumor-suppressor genes: ATM (NPAT) with four analyzed CpG sites (CpG 1–4), PITX2 (CpG 1–5), RASSF1 (CpG 1–3), PTEN (CpG 1–6), and TIMP3 (CpG 1–6)." (PMID 40371330, 2025). "Epigenetic analyses revealed histone modifications (H4K16ac, H4K20me3) and altered methylation of tumor-suppressor genes (PITX2, RASSF1, PTEN, TIMP3)." (PMID 40371330, 2025). "Gene promoter methylation analysis of the following tumor-suppressors was realized: ATM comprising four evaluated CpG sites (CpG 1–4), PITX2 (CpG 1–5), RASSF1 (CpG 1–3), PTEN (CpG 1–6), and TIMP3 (CpG 1–6)." (PMID 38464730, 2024).
tumor (continued). "RASSF1 and 3 contain a SARAH-domain that intervenes in the regulation of MST1 and MST2 kinases in the activation of YAP, an activity crucial to its tumour suppressor function." (PMID 36765842, 2023). "In SCC, genes that are commonly hypermethylated to repress their expression and tumor-suppressive activities include CDKN2A and RASSF1 (growth arrest), MGMT (DNA repair), and DAPK (apoptosis)." (PMID 35912167, 2022). "During tumor progression, specific gene promoters and CpG islands are hypermethylated, leading to silencing of genes including tumor-suppressor genes like APC and RASSF1." (PMID 35272673, 2022). "RASSF1 is a putative tumor suppressor gene that controls tumor growth by inhibiting the RAS pathway and RASSF1A, one of the seven transcript isoforms of RASSF143, is frequently inactivated via methylation." (PMID 35013462, 2022). "RASSF1A, one of the eight isoforms of the RASSF1 gene, is a tumor suppressor gene that influences tumor initiation and development." (PMID 33175673, 2021). "Aberrant methylation of repeat sequences like LINE1 or tumor suppressors such as DAPK, RASSF1 and, ECAD is undoubtedly crucial in tumor progression." (PMID 31712935, 2020). "The methylation status of five tumor-suppressor gene promoters was assessed: ATM including four evaluated CpG sites (CpG 1–4), PITX2 (CpG 1–5), RASSF1 (CpG 1–3), PTEN (CpG 1–6), and TIMP3 (CpG 1–6)." (PMID 33375383, 2020). "A recent study showed that overexpression of RASSF1 in HCC cells induced autophagy via inhibiting PI3K-AKT-mTOR signaling through the Hippo pathway module MST1 and suppressed HCC tumor growth." (PMID 31409760, 2019). "RASSF1A hypermethylation being a key early event during carcinogenesis, the detection of a methylated RASSF1 promoter in plasma circulating tumor DNA is an attractive biomarker for early detection of various cancers." (PMID 31804463, 2019). "Herein, we focused on the epigenetic impact on OC formation by analysing the methylation levels of the RASSF1, PTEN, CDH1 and PAX1 tumour suppressor genes’ regulatory sequences." (PMID 31450846, 2019). "Both RASSF1‐methylated and low RASSF1A mRNA tumours display signatures of embryonic stem cells and are poorly differentiated." (PMID 31268606, 2019). "Of interest, the degree of promoter methylation was associated with tumor grade, while there was a non-linear correlation between levels of methylation and RASSF1 mRNA or protein content, thus suggesting that other transcriptional or post-transcriptional events may concur in its regulation." (PMID 27418145, 2016). "Recent reports demonstrate promoter methylation of tumor-related genes, including MGMT, CDKN2B and RASSF1." (PMID 26675260, 2016). "We identified a significant difference in RASSF1 methylation levels between FTC-Classic and FTC-Hurthle tumor tissues (p<0.001) as well as between the adjacent normal tissues (p=0.01) of these two subtypes." (PMID 27158284, 2015). "In this study, RASSF1 and RASSF2 were hypermethylated in cell lines representative of tumor subtypes with best and worst prognosis, respectively." (PMID 26284587, 2015). "Some of these genes, e.g., RASSF1, NPRL2, and SEMA3B, suppress the growth of tumor cells in vitro and in vivo." (PMID 25961819, 2015). "Of the 16 tumor-normal pairs with presumed hypermethylated promoter loci in HCC (in genes BMP4, RASSF1,GSTP1, and TACSTD2), 5, 6, 14 and 16 of the 16 HCCs had decreased expression of the gene, respectively." (PMID 23437062, 2013). "Five hypermethylated loci harbored by four genes (GSTP1, TACSTD2, BMP4 and RASSF1) and three hypomethylated loci in three genes (ARHGAP8, GPR35 and DLGAP1) were validated using 7 assays with 12 tumor-normal tissue pairs from this study." (PMID 23437062, 2013). "RASSF1A, one of the seven different isoforms of RASSF1, is a putative tumor suppressor gene located on 3p21, a region of common heterozygous and homozygous deletions in different types of human tumors." (PMID 23139773, 2012).
tumor (continued). "The importance of promoter hypermethylation in silencing critical tumor-suppressors (e.g., APC, RASSF1) in PCa is well documented." (PMID 22547956, 2011). "It has been reported that the expression of RASSF1 and FHIT is inhibited in NSCLC tumours, their downregulation interestingly also having been shown to be associated with promoter hypermethylation." (PMID 20736951, 2010). "Identification of genes with subtype-specific methylation revealed that, for example, RASSF1 and GSTP1 were specifically methylated in lumB tumours and unmethylated in basal-like tumours." (PMID 20565864, 2010). "The candidate region on 3p21.3 harbors various tumor suppressor genes (HYAL2, FUS1, RASSF1, BLU, NPR2L, CYB561D2, PL6 and CACNA2D2)." (PMID 20678252, 2010). "Genes promoting cancer progression (u-PAR, VEGFC, and HIF1α) and tumour suppression (VHL, RASSF1, and FHIT) of NSCLC were significantly (P<0.05) down- or upregulated after Enz treatment in H460, A549, and H1299 cells, respectively." (PMID 20736951, 2010). "We focused in those genes that were significantly differently methylated in the basal-like tumor subtype (HOXA9, SOX1, VAMP8, and TNFRS10D) and those that were significantly hypermethylated in the luminal B tumors (NPY, RASSF1, HS3ST2, DBC1, FGF2, CD40." (PMID 20920229, 2010). "Tumour-suppressor genes VHL, RASSF1, and FHIT are downregulated in NSCLC, which are implicated in the ubiquitin ligase system, cell-cycle regulation, and apoptosis, respectively." (PMID 20736951, 2010). "The identified genes are involved in drug transport and detoxification (ABCB1, DNAJC15, GSTP1, RAB6C), DNA damage repair (BRCA1) as well as tumor cell proliferation/invasion (APC, CDH1, ESR1, HIC, PLAU, RASSF1, SULF2, TGM2)." (PMID 20544021, 2010). "Six loci (CLEC3B (previously TNA), MGP, RASSF1, SDK2, SERPINB5 and XAGE1A (previously GAGED2)) with statistically significantly higher methylation in tumor samples compared with non-tumor samples were identified." (PMID 18947422, 2008). "Other assays such as SelectMDx and ConfirmMDx detect DNA hypermethylation patterns in tumor suppressor genes (e.g., GSTP1, RASSF1), which are influenced by the availability of metabolic cofactors like S-adenosylmethionine (SAM) and acetyl-CoA—central intermediates in epigenetic regulation." (PMID 40649790, 2025). "Consistent with this, we did not see a difference in RASSF1 expression in tumor samples defined by EBV status, but there was a significantly lower expression of HOPX in EBV+ tumors." (PMID 41280003, 2025). "Restoring tumour suppressors such as HNF4A and RASSF1 could further improve outcomes, though this remains an area of active research." (PMID 41007296, 2025). "Additionally, comparable to hypermethylation of RASSF1, hypermethylation of TMEM240 and DHRS3 have been described in several types of cancers, and these genes have been proposed as tumour suppressor genes." (PMID 39589853, 2025). "Evaluation of three other tumor-suppressor gene promoters revealed no significant changes, although methylation status was reduced by 11% in RASSF1 and ATM genes after higher aronia dosing." (PMID 39435289, 2024). "RASSF1 is a tumor suppressor involved in cell cycle regulation and not previously linked to unfolded protein response (UPR)." (PMID 36723232, 2023). "We first investigated the methylation of all the promoters of the genes involved in the RASSF/Hippo pathway, specifically RASSF1/2, STRK4/3 (coding for MST1 and MST2 proteins respectively), and LATS1/2, by MS-PCR using DNA extracted from the tumour blocks of 100 patients." (PMID 34885067, 2021). "Thyme haulm was administrated in a diet, and an evaluation of the DNA methylation status of five promoters of tumor-suppressor genes (ATM, PITX2, RASSF1, PTEN, and TIMP3) showed significant decreases in methylation patterns in vivo after intervention with thyme." (PMID 31323834, 2019).
tumor (continued). "In addition, the protein levels of Rassf1, Mst1, Mst2, Sav1, Mob1, and p-Mob1 were increased, whereas those of YAP and CTGF were diminished in UA-treated xenograft tumor tissues." (PMID 31547587, 2019). "In the second node, higher methylation of either RASSF1 or RARB was able to separate the remaining tumor from the benign samples (data not shown)." (PMID 29851970, 2018). "Our present investigation had covered a broad group of tumor-related pathway genes, including p16 (cell-cycle control), DAPK, RASSF1 (apoptosis), BRCA1, MLH1 (DNA repair), ECAD (cell-cell adhesion), GSTP1 (carcinogen metabolism), MINT1, MINT2 and MINT31 (methylated loci in tumors)." (PMID 26098903, 2015). "Field effects for DNA methylation changes in RASSF1, EGFR and TFF1 might be important in influencing pre-neoplastic changes in gene expression relevant to tumor development." (PMID 26510686, 2015). "Here, in this study, we analyzed the aberrant promoter methylation profile of HNSCC using seven important tumor-related pathway genes (p16, DAPK, GSTP1, ECAD, RASSF1, MLH1 and BRCA1) and three methylated loci (MINT1, MINT2 and MINT31) in the high cancer incidence zone of Northeast India." (PMID 26098903, 2015). "Frag_01, Frag_02 and ZIC4 present a much lower P-value, indicating they may be better tumor markers than CDKN2A and RASSF1." (PMID 22726460, 2012). "Moreover, we show that u-PAR, VEGFC, and HIF1α, among other targets, are being downregulated, and the tumour-suppressor genes FHIT, RASSF1, and VHL are upregulated upon Enz treatment." (PMID 20736951, 2010). "Moreover, remarkably, it significantly upregulates the tumour-suppressor genes (FHIT, RASSF1, and VHL) that are known to be downregulated in NSCLC." (PMID 20736951, 2010). "The expression levels of EGF-EGFR-RAS signaling marker genes EGF, EGFR, HRAS, RASSF1 and STK4 in the HLX22 and HLX02 combination-treated cells decreased, suggesting that HLX22 in combination with HLX02 inhibited EGF-EGFR-RAS signaling to suppress tumor proliferation, survival, and invasion." (PMID 38982548, 2024). "Thus, it is tempting to speculate that, at least some of the genes detected here (e.g., RASSF1 and GSTP1) could be constitutionally methylated and, in such cases, methylated tumor cells may have originated from the constitutionally methylated normal cells." (PMID 32859265, 2020). "Isoform RASSF1C is highly expressed in PET at variance with the other six isoforms generated from RASSF1 locus; this suggesting that RASSF1C might play a pathogenetic role in tumor development, in the light of the recent demonstration of its involvement in the regulation of Wnt pathway." (PMID 21838870, 2011). "Apart from its pro-apoptotic, growth inhibitory, and anti-angiogenic properties, this could be, at least in part, due to downregulating tumour progression and invasion-related genes (u-PAR, HIF1α, and VEGFC) and upregulating NSCLC tumour-related suppressor genes (FHIT, RASSF1, and VHL) by Enz." (PMID 20736951, 2010). "The comparison of the findings in the tumor tissue and in the peripheral blood from the same patient showed no RASSF1 or CDKN2A methylation in any of the peripheral blood samples, and only one sample positive for MGMT methylation; a T4N0 M0 (stage IVa) squamous cancer of the oral cavity." (PMID 19807915, 2009). "Notably, further complexity arose with the identification of RAS effectors (e.g. RASSF1-2 or NORE1) with putative tumor suppressor, rather than oncogenic functions." (PMID 17311103, 2007).
tumor (continued). "Thus, it is intriguing to speculate that restoring IGFBP3 expression and/or use of demethylating drugs could contribute to new therapeutic strategies for HB, especially with the existence of additional epigenetically silenced genes in this tumor type, such as HHIP, RASSF1, SOCS1, APC and CASP8." (PMID 22401581, 2012). "When comparing RASSF1 methylation levels between the tumor tissue and adjacent normal within an FTC subtype in the current study, as expected, the tumor tissue demonstrated higher methylation levels." (PMID 27158284, 2015). "Moreover, we found all CpG sites for RASSF1 and APC, but none for GSTP1, to have significantly higher methylation levels in ER-positive than in ER-negative tumours." (PMID 20565864, 2010).